NLRP3 (NLR family pyrin domain containing 3)
Diseases named in the same sentence as NLRP3 in open-access papers (continued):
Sharing a sentence is not in itself a finding about the gene and the disease.
Insulin resistance (continued). "However, invalidation of different components of the NLRP3 inflammasome (NLRP3, ASC, caspase-1) univocally protected the mice against high-fat diet-induced inflammation and insulin resistance." (PMID 23316186, 2012). "However, a recent study found that insulin resistance and liver histopathology in metabolically unhealthy subjects did not correlate with the hepatic abundance of NLRP3 inflammasome nor circulating IL-1β levels." (PMID 36817440, 2023). "A previous study showed that NG‐R1 administration ameliorated cognitive dysfunctions, insulin resistance, dyslipidemia, inflammation, and oxidative stress by activating Akt/Nrf2/HO‐1 pathway and inhibiting NOD‐like receptor family pyrin domain‐containing 3 (NLRP3) inflammasome in db/db mice." (PMID 38107110, 2023). "It was found that endogenously synthesized n-3 PUFA blocked HF diet-induced NLRP3 inflammasome activation and the release of IL-1β in adipose tissue, stromal vascular fraction (SVF) and adipose tissue preadipocytes, which attenuated insulin resistance in HF diet-fed fat-1 mice." (PMID 36234919, 2022). "The activation of the NLRP3 inflammasome could enhance the expression of IL-1β, IL-18, and interferonγ (IFNγ), while it inhibits IRS-1/PI3K/AKT signaling, thereby leading to insulin resistance." (PMID 36187801, 2022). "Therefore, we decided to evaluate the expression of GLUT4 and IRAP markers as well as insulin mRNA in animals that do not express NLRP3 inflammasomes to assess the contribution of neuroinflammation to the development of insulin resistance." (PMID 34769018, 2021). "Components of the NLRP3 inflammasome complex and proinflammatory markers were analyzed in livers to test whether NPRP3 inflammasome and related hepatic metaflammation participate in verapamil-mediated improvements in hepatic steatosis and insulin resistance." (PMID 30429827, 2018). "Interestingly, both NLRP3 and TXNIP knockout mice have reduced insulin resistance." (PMID 28348460, 2017). "Accordingly, given that lack of Nlrp3 did not abrogate Western diet-induced AT inflammation, it is not entirely surprising that glucose intolerance and increased fasting HOMA-IR, both indicators of insulin resistance, were not reduced in Nlrp3-/- mice relative to WT mice." (PMID 27583382, 2016). "We can speculate that in a condition of insulin-resistance (IR), several extracellular and intracellular stimuli, i.e., free fatty acids (FFA), ionic flux, extracellular ATP (eATP) and ROS may be increased and activate NLRP3 inflammasome and the release of IL-1β." (PMID 40526637, 2025). "Although this ceramide-NLRP3 inflammasome interaction may contribute to adipose inflammation, which contributes to insulin resistance in rodent and human adipocytes, direct evidence regarding the role of sphingolipids in bovine adipose or their ability to regulate NLRP3 and inflammation is lacking." (PMID 38274826, 2023). "Thus, neither with aging nor with NLRP3 KO were the signs of insulin resistance revealed." (PMID 38068904, 2023). "In this study, a HF diet activated NLRP3 inflammasome via inducing reactive oxygen species (ROS) generation and promoted IL-1β production primarily from adipose tissue preadipocytes, but not from adipocytes and induced insulin resistance in wild type (WT) mice." (PMID 36234919, 2022). "Therefore, the decreased number of hepatic macrophages and their M2-dominant polarization account, at least in part, for the attenuation of insulin resistance and steatohepatitis in febuxostat-treated CL diet-fed mice, even though the mRNA expression of Nlrp3 or Il-1β in the liver is not decreased." (PMID 31965018, 2020). "Plasma glucose and in particular insulin levels and insulin resistance, as assessed by HOMA-IR, were all elevated in obese WT mice, with no significant changes in Nlrp3−/− and Asc−/− (Pycard−/−) mice." (PMID 31379826, 2019).
Cognitive impairment (274 papers, 2015 to 2026). Abnormal cognition is characterized by deficits in thinking, reasoning, or remembering. "In a homocysteine-induced cognitive impairment model, an independent risk factor for AD, betaine alleviated cognitive impairment by inhibiting the NLRP3/caspase-1/GSDMD pathway in an m6A-YTHDF2-dependent manner, thereby suppressing microglial pyroptosis." (PMID 41608511, 2026). "DHQ exerts a mitigating effect on age-associated cognitive impairment, possibly through its association with reduced neuroinflammation and dual modulation of neuronal apoptosis and the NLRP3 inflammasome-mediated pyroptosis pathway." (PMID 41710929, 2026). "Our results suggest that A. muciniphila holds promise as a probiotic for treating NLRP3‐associated inflammatory disorders and cognitive impairment, including MS." (PMID 40050112, 2025). "The consequences of NLRP3 activation include cognitive impairment, neuronal loss, and neuroinflammation." (PMID 41488618, 2025). "From a translation point of view, our results indicate that styrene exposure can be a high-risk factor for developing cognitive deficits and suggest considering the ROS/NLRP3 pathway as a target to prevent/attenuate neurotoxicity." (PMID 41324731, 2025). "We demonstrate for the first time that targeting NLRP3, post-symptomatic establishment, rescues cognitive deficits, mitigates neuronal loss, and is sufficient to significantly reduce reactive microgliosis, neuroinflammation and tau pathology." (PMID 40343261, 2025). "While this mechanism is linked to cognitive deficits in animal models, the inhibition of the tau and NLRP3 interaction effectively reduces NLRP3 acetylation and cognitive impairment." (PMID 40427569, 2025). "Together, these findings suggest that HFD‐induced cognitive impairments in 3xTg‐AD mice are closely associated with increased insoluble tau aggregates and NLRP3 inflammasome activation in the hippocampus." (PMID 40589337, 2025). "In this study, we first demonstrated that NLRP3-mediated pyroptosis was closely related to the CKD-associated cognitive impairment." (PMID 39698584, 2024). "The continuous activation of neuroinflammation markers such as NOD-, LRR, pyrin domain-containing protein 3 (NLRP3), and high-mobility group box 1 (HMGB1) has been shown to be associated with cognitive impairment in NLRP3-knockout mice after TBI." (PMID 39063593, 2024). "The NLRP3 inflammasome’s activation by the virus’s protein is linked to respiratory distress and cognitive impairment." (PMID 38543856, 2024). "The nucleotide-binding oligomerization domain-like receptor 3 (NLRP3) inflammasome has been poorly studied as a regulator of neuroinflammation in cognitive impairment caused by intermittent hypoxia." (PMID 37312196, 2023). "The cognitive deficits in P7 neonatal rats induced by clinical doses of ketamine (20 mg/kg) are associated with hippocampal NLRP3 inflammasome activation." (PMID 36776829, 2023). "Cognitive impairment caused by various diseases is associated with the activation of NLRP3 inflammasome." (PMID 37165444, 2023). "Increasing evidences revealed a causal relationship between sevoflurane-induced cognitive impairment and NLRP3 inflammasomes in hippocampus." (PMID 36696410, 2023). "Previous studies have shown that the NLRP3 inflammasome is associated with many neurodegenerative diseases, such as type 2 diabetes (T2D) and PD, and cognitive impairment caused by surgery and anesthesia." (PMID 36934348, 2023). "In the current study, we identified NLRP3 inflammasomes activation as a cause of sevoflurane-induced cognitive impairment." (PMID 36696410, 2023). "Studies have shown that the P2X7R/NLRP3 signaling mediates inflammatory responses and cell death, including pyroptosis, and is associated with cognitive impairment in neurological diseases such as AD, and diabetes." (PMID 37915104, 2023).
Cognitive impairment (continued). "In recent studies, NLRP3 is significantly increased in the PNDs mouse model and is associated with isoflurane-induced cognitive impairment." (PMID 36688154, 2022). "In summary, lncRNA 4344 is involved in neuroinflammatory processes in neurological disorders associated with cognitive disorders by competitively binding to miR-138-5p, thereby indirectly up-regulating the expression of inflammasome NLRP3." (PMID 36034298, 2022). "An animal experiment suggested the involvement of NLRP3 priming status in the brains of old mice in the causation of isoflurane-induced cognitive impairment and hippocampal inflammation." (PMID 36406365, 2022). "NOD-like receptor family, pyrin domain-containing 3 (NLRP3)-null mutation from visceral adipose tissue (VAT) prevents cognitive impairment in mice with Alzheimer's disease." (PMID 35280695, 2022). "The ASA treatment caused a significant decrease (p < 0.0001) in the NLRP3 and IL-1β brain expression and was able to ameliorate the process of neuroinflammation and consequently the cognitive impairment induced by the administration of alcohol and/or ATOR." (PMID 35335908, 2022). "Results showed that the intracerebroventricular (icv) injection of streptozotocin (STZ) activated the NLRP3 inflammasome, reduced Aβ clearance, and induced neuronal loss and cognitive impairment." (PMID 34209586, 2021). "Our results show that NLRP3 inflammasome activation is an important cause of cognitive impairment after TBI." (PMID 34666797, 2021). "NLRP3 recognizes the microbe-associated molecular patterns expressed by gut microbiota, and changes in microbial composition are associated with increased levels of NLRP3 in the plasma of patients with cognitive impairment and brain amyloidosis." (PMID 33916001, 2021). "Our previous study found that miR-138-5p plays a vital role in neuroinflammation by targeting NLRP3 and this phenomenon can cause cognitive impairment." (PMID 34599154, 2021). "The NACHT, LRR, and pyrin (PYD) domain-containing protein 3 (NLRP3) inflammasome is implicated in both gut immune homeostasis and neuroinflammation, and activation was found to exacerbate Aβ deposition and cognitive impairment in AD." (PMID 34229722, 2021). "ASC or NLRP3 deficiency was reported to reduce tau pathology and protect against cognitive impairment in tau transgenic mice." (PMID 33525754, 2021). "First, NLRP3 was shown as critical immune sensors that causally link systemic inflammation to aging and cognitive disorder." (PMID 34924922, 2021). "The neuroinflammatory response is generally believed to be regulated by NLRP3 inflammasome-dependent pyroptosis of neurons, and the death of neurons caused by pyroptosis is closely related to the onset of cognitive impairment." (PMID 33204250, 2020). "Recent studies have revealed that isoflurane-induced cognitive impairment was associated with high levels of NLRP3 in the hippocampus of aged mice and the impairment was reversed by the inhibition of NLRP3-caspase-1 pathway." (PMID 30873011, 2019). "Altogether, previous studies as well as our study suggest that NLRP3 inflammasome-dependent pyroptosis is a key regulator of the underlying mechanisms of isoflurane-induced neuronal damage and cognitive impairment in aged mice." (PMID 30524241, 2018). "Nod-like receptor protein 3 (NLRP3) inflammasome activation has been implicated in the pathogenesis of general anesthesia (GA)-induced neuroinflammation and cognitive impairment in aged rodents." (PMID 30524241, 2018). "In conclusion, our results suggest that isoflurane-induced cognitive deficits are associated with generation of mtROS, which activates the NLRP3 inflammasome and the apoptotic Cyt C-caspase 3 signaling pathway." (PMID 26379247, 2015). "Here, we assessed whether inhibiting NLRP3 can ameliorate cognitive deficits, gut abnormalities, gut microbial alteration, and associated molecular and behavioural disturbances in HD." (PMID 41906693, 2026).
Cognitive impairment (continued). "Similarly, NLRP3 inflammosomes have been implicated in cognitive impairment, whereas PDGFC signaling has been previously known to ameliorate neuroinflammation by blood–brain barrier disruption in mouse models." (PMID 40665476, 2025). "Targeting the NLRP3 inflammasome within the MGBA could offer therapeutic strategies for cognitive impairment associated with sleep disorders." (PMID 41458114, 2025). "Therefore, our findings indicated that mitophagy-mediated inhibition of the NLRP3 inflammasome was associated with improvement in anesthesia/surgery-induced cognitive impairment." (PMID 38145993, 2024). "The present study first prompted that irisin could attenuate CKD-associated cognitive impairment through inhibiting AhR/NF-κB/NLRP3-mediated hippocampal neurons pyroptosis." (PMID 39698584, 2024). "Combined with the behavioural results, we speculate that the cognitive impairment caused by Tau441 and TauS262E overexpression may be linked to their effects on the activation of NLRP3 inflammasome in microglia and promotion of microglia activation." (PMID 38488468, 2024). "Additionally, repeated exposure to propofol causes upregulation of NF-κB and the NLRP3 inflammasome, resulting in long-term cognitive impairment in the brains of neonatal and aged rats." (PMID 37962460, 2024). "Similarly, we found that increased circulating ADMA in young male rats changed the microbiota composition and intestinal NLRP3 activation, which were associated with dorsal hippocampal NLRP3 activation and cognition impairment." (PMID 37375772, 2023). "In conclusion, NLRP3 inflammasome may be a regulatory target for ameliorating cognitive impairment caused by intermittent hypoxia, and microglial exosomal miR-146a-5p may be a promising therapeutic strategy." (PMID 37312196, 2023). "Using an EAE rodent model, investigators found that hippocampal synapse loss could be ameliorated with an NLRP3 inflammasome inhibitor, corresponding with reduced development of memory and cognitive deficits in advanced stages of disease." (PMID 36915214, 2023). "Taken together, this current study suggests that anesthesia and surgical exposure in aged mice cause impulsive-like behaviors and cognitive impairment, which may be associated with increased NLRP3 activity in astrocytes." (PMID 37434240, 2023). "This study may provide evidence to develop specific drugs or therapies to reduce NLRP3-induced cognitive impairment-associated PND and to improve prognosis." (PMID 36406365, 2022). "In conclusion, our study showed that hippocampal inflammation and NLRP3 inflammasome activation were linked to tibial fracture surgery-induced cognitive impairment in aged mice, which could be alleviated by presupplementing with VD3." (PMID 36880085, 2022). "Studies have proven that the cognitive impairment caused by isoflurane is related to the high expression of hippocampus NLRP3, and this damage could be reversed by inhibiting the NLRP3-caspase-1 pathway." (PMID 35153623, 2022). "Notably, NLRP3 inflammasome deficiency prevented cognitive impairment, indicating that NLRP3 inflammasome-mediated neuroinflammation is a central driver of the progression of CKD-related cognitive dysfunction." (PMID 34572437, 2021). "Moreover, ASC or NLRP3 deficiencies have been associated with a decreased tau pathology and protected tau transgenic mice against cognitive impairment." (PMID 34209586, 2021). "Additionally, in vivo blockage of NLRP3 inflammasome with MCC950 in early life of NEC pups potently protected against NEC-associated long-term cognitive impairment." (PMID 33676524, 2021). "A suggestion that could be driven from this study is that NLRP3/IL-1β signaling could underlie correlations between visceral adiposity and cognitive impairment not only in mice but also in humans." (PMID 34070553, 2021). "NLRP3/IL-1β signaling could underlie the association between adiposity and cognitive impairment in humans." (PMID 34070553, 2021).
Cognitive impairment (continued). "As we had established that zinc deficiency could potentiate NLRP3 responses in vitro, we hypothesized that zinc deficiency accelerated cognitive impairment in the APP/PS1 mouse via the NLRP3 inflammasome." (PMID 33597269, 2021). "An NLRP3-caspase-1 pathway inhibitor could attenuate the cognitive impairment caused by isoflurane anesthesia in the aged mice." (PMID 29665808, 2018). "In addition, recent studies have revealed that dysregulation of NLRP3 inflammasome was associated with cognitive impairment, and the impairment could be reversed by inhibiting the NLRP3 inflammasome." (PMID 35955939, 2022). "Therefore, NLRP3 inflammasome may be the main cause of cognitive impairment after surgery as well as scopolamine treatment." (PMID 33863952, 2021). "Therefore, we hypothesize that canonical NLRP3 inflammasome/IL-1β axis is likely is implicated in postoperative inflammatory mediators-induced cognitive impairment." (PMID 30873011, 2019). "Furthermore, preliminary experimental findings have suggested that NLRP3 inflammasome activation was linked to cognitive impairment after isoflurane anesthesia and isoflurane exposure induced the upregulation of NLRP3 and subsequently increased the level of IL-1β in the hippocampus of aged mice." (PMID 30873011, 2019). "Besides, the involvement of NLRP3 inflammasome activation might lead to new insights into the underlying pathophysiology of cognition impairment." (PMID 28582770, 2017). "Retinal NLRP3 is elevated in mild cognitive impairment and activated in AD dementia, evidenced by increased caspase-1, cleaved interleukin-1β, and cleaved N-terminal gasdermin-D." (PMID 41571675, 2026). "Blocking NLRP3 inflammasome signaling effectively reduces Aβ deposition and alleviates cognitive impairments in diseased mice." (PMID 41551989, 2026). "Treatment with A. muciniphila reduced regulated cognitive impairment and hippocampal NLRP3-mediated neuroinflammation through improving intestinal barrier function and attenuating Th17 responses in the gut, central nervous system, and lymphoid tissues of mice." (PMID 40860878, 2025). "This release activates the cGAS–STING signaling pathway, promoting microglial activation and NLRP3 inflammasome assembly, thereby exacerbating postoperative cognitive impairment." (PMID 40914484, 2025). "In this work, we also evaluated the influence of the NLRP3 inflammasome on the cognitive impairments provoked by PTX by assessing the effects of the MCC950 treatment on novel object recognition test performance." (PMID 40002330, 2025). "Accordingly, this study aimed to investigate the effects of NTN-1 on cognitive impairment and to explore the anti-inflammatory properties related to the NLRP3 inflammasome and NF-κB signaling in Aβ1-42-induced rat models." (PMID 40357234, 2025). "This study suggests that W. coagulans BC99 indirectly improves cognitive impairment by inhibiting the expression of NLRP3/ASC signaling in the intestinal tract of SD mice." (PMID 40232008, 2025). "These have been reported to decrease inflammasome components levels, reduce neuroinflammation and Aβ plaques and improve cognitive impairment in AD mouse models by directly blocking NLRP3 activity." (PMID 41280719, 2025). "GAS-5 is correlated with NLRP3 activation and the progression of cognitive impairment in Parkinson’s disease." (PMID 40257540, 2025). "Developmental As(III) exposure induces cognitive deficits in offspring rats by activating the NLRP3 inflammasome in the hippocampal microglia." (PMID 40710983, 2025). "GAS-5 is correlated to NLRP3 activation and the progression of cognitive impairment in Parkinson’s disease." (PMID 40257540, 2025). "This evidence reinforces NLRP3’s potential as a therapeutic target for mitigating neuroinflammation and improving outcomes in HIV-associated cognitive impairment." (PMID 41280902, 2025).